IGF2BP1 (insulin like growth factor 2 mRNA binding protein 1)
Diseases named in the same sentence as IGF2BP1 in open-access papers (continued):
Sharing a sentence is not in itself a finding about the gene and the disease.
tumor (continued). "High levels of IGF2BP1 are correlated with larger tumor size, lymph node metastasis, and poorer survival rates in patients with HCC." (PMID 38566136, 2024). "Overall, these results indicated that IGF2BP1 plays a significant part in promoting the malignant biological behavior of HNSC tumor cells." (PMID 39512352, 2024). "Numerous associated studies have reported the augmentation or resynthesis of IGF2BP1 expression in human tumours and animal models, indicating that IGF2BP1 is crucial for the growth of tumour tissue." (PMID 39679845, 2024). "In the Swartling meta-analysis, IGF2BP1 was also over-expressed compared to that of non-tumor samples." (PMID 39062749, 2024). "The tumor volume and weight analysis revealed that IGF2BP1 silencing inhibited the volume and weight." (PMID 39606242, 2024). "This compound specifically targeted c-Myc mRNA, downregulated β-TrCP1 mRNA, reduced NF-κB activity, and inhibited the proliferation and protein synthesis of IGF2BP1-positive tumor cells." (PMID 39342091, 2024). "IGF2BP1 promotes the proliferation, survival, and invasion of tumor cells through both m6A-dependent and non-m6A-dependent mechanisms." (PMID 39342091, 2024). "Genome-wide cross-linking and immunoprecipitation (CLIP) studies identified a large number of IGF2BP1 targets, suggesting roles in cell growth, migration, synaptic plasticity in healthy tissues, as well as tumor growth and metastasis in cancer cells." (PMID 39426983, 2024). "IGF2BP1 is highly conserved across mammals and is widely expressed during the embryonic stage and in various tumor tissues." (PMID 39342091, 2024). "The IGF2BP1-OE NCI-H929 cells (1731.0 ± 535.1 mm3) showed a ∼2.13-fold increase in tumor volume compared with the IGF2BP1-NC cells (813.2 ± 171.7 mm3) (day 14, P = 0.036; day 17, P = 0.002; day 19, P = 0.036; day 21, P = 0.017)." (PMID 39534570, 2024). "In conclusion, IGF2BP1 can be recruited by a variety of viruses from distinct families to promote their spreading, and thus, anti-tumor strategies aiming to inhibit the expression or function of IGF2BP1 should be tested for anti-viral effects as well." (PMID 37515119, 2023). "IGF2BP3 shares 73% amino acid sequence identity with IGF2BP1 and is particularly interesting in tumorigenesis and tumor progression." (PMID 37426488, 2023). "IGF2BP1 expression was essential for tumor cell survival in multiple ETV6::RUNX1 positive B-ALL cell lines." (PMID 37670323, 2023). "In 62 EBVaGC tumour tissues from the SYSUCC cohort, FOS expression was detected to be positively correlated with IGF2BP1/2 expression, suggesting an underlying positive regulatory mechanism." (PMID 38082402, 2023). "The analysis of tumor’s size revealed that SM1 Igf2bp1-KO tumors grew slower compared to SM1 CRISPR/Cas9 control." (PMID 37503349, 2023). "IGF2BP1 is believed to promote the proliferation, migration, invasion, and metastasis of tumor cells." (PMID 37137887, 2023). "Igf2bp1 genetic inhibition increased tumor immunogenicity, which is in line with a recently published study." (PMID 37503349, 2023). "IGF2BP1 participates in the glycolysis of tumour cells and plays a significant role in the formation of acidic TME and the occurrence of immune escape." (PMID 36747239, 2023). "Ethical culling was required after 169–305 d (median survival 234 d), suggesting a strongly IGF2BP1-dose dependent tumor induction." (PMID 37246217, 2023). "The results showed conspicuously higher RBMX, FMR1 and IGF2BP1 expression in tumor tissues, especially RBMX." (PMID 37194014, 2023). "Previous studies identified that IGF2BP1 promoted tumor progression, which contributed to the malignant phenotypes of tumor cells, and multiple types of human cancers showed poor OS and metastasis when IGF2BP1 was upregulated." (PMID 36966311, 2023). "Although circRNAs related to tumor immunity regulation have been partially identified, circCRIM1 was distinguished by its role in influencing tumor immune evasion by combining with IGF2BP1." (PMID 36672208, 2023).
tumor (continued). "Here, we revealed the novel role of the circRNA/IGF2BP1 complex to regulate tumor immune evasion, which would broaden the understanding of circRNAs in tumor immunity." (PMID 36672208, 2023). "Insulin-like growth factor 2 mRNA-binding proteins (IGF2BP1-3) are a class of m6A binding proteins that promote the stability and expression of target genes, exhibiting oncogenic activity in tumours." (PMID 36859310, 2023). "In the present study, we identified INHBA as a direct target of IGF2BP1 with a functional role in tumor invasion induced by IGF2BP1." (PMID 37644505, 2023). "IGF2BP1 overexpression was detected in ESCC tissues and associated with the depth of tumor invasion." (PMID 37644505, 2023). "Various studies have confirmed that IGF2BP1 can act as an oncogene in multiple tumors and promote tumor cell proliferation, invasion and chemotherapy resistance." (PMID 37304234, 2023). "METTL3-mediated m6A decoration is essential for promoting tumour PD-L1 expression through IGF2BP1-enhanced RNA stability in bladder cancer, and the activation of JNK signalling augments METTL3 expression." (PMID 36859310, 2023). "In BCa, IGF2BP1 promotes tumour proliferation, migration and invasion by regulating the expression of MYC and FSCN1." (PMID 36747239, 2023). "Seven out of eight IGF2BP1-induced tumors resided in the lower abdomen, potentially arising from sympathetic nerves, and only one homozygous tumor was derived from the adrenal gland." (PMID 37246217, 2023). "Distinguishingly, IGF2BP2 is ubiquitously expressed in normal adult and tumor tissues, whereas IGF2BP1 and IGF2BP3 are de novo synthesized during numerous malignancies, earning themselves the label of bona fide oncofetal proteins." (PMID 37554271, 2023). "To achieve this, we computed a Spearman correlation in the expression of 17 gene signatures with IGF2BP1 in COAD tumor dataset using GEPIA2." (PMID 37829185, 2023). "In particular, tumor-promoting viruses, such as hepatitis B/C and human papillomaviruses, benefit from IGF2BP1." (PMID 37515119, 2023). "Activation of the Wnt/β-Catenin-IGF2BP1 pathway in cancer cells leads to increased gene expression of a subset of genes, promoting an aggressive tumor phenotype and unfavorable prognostic outcomes." (PMID 37829185, 2023). "This study identifies circCRIM1 as a new tumor suppressor that inhibits tumor immune evasion through a competitive combination with IGF2BP1 to destabilize HLA-F mRNA." (PMID 36672208, 2023). "Elevated expression of IGF2BP1 can be found in primary tumor tissues such as breast, colon, and non-small cell lung cancers." (PMID 37631029, 2023). "In subcutaneous (s.c.)xenografts, IGF2BP1-KO impaired tumor engraftment, MYCN expression and delayed growth by 5–7 days." (PMID 37246217, 2023). "We evaluated the relationship between expression patterns of RBMX, FMR1, LRPPRC, YTHDC2, IGF2BP1 and clinical parameters, including stage, T (tumor infiltration), N (lymphatic metastasis), M (distant metastasis) in CRC." (PMID 37194014, 2023). "After further screening, we evaluated the relationship between expression of FMR1, LRPPRC, RBMX, YTHDC2, IGF2BP1 and clinical parameters, including stage, T (tumor infiltrating), N (lymphatic metastasis) and M (distant metastasis) in CRC." (PMID 37194014, 2023). "Together with data from knockout mouse models, IGF2BP1 seems to enhance an aggressive tumor cell phenotype by antagonizing miRNA-impaired gene expression." (PMID 37885041, 2023). "Consistently, IGF2BP1 is a prognostic factor in abundant human cancers with high expression in tumor tissue." (PMID 37426488, 2023). "The inhibition of IGF2BP1, as a crucial m6A reader protein, exerts a tumor suppressor effect in HCC by inducing apoptosis and subsequently activating immune cell infiltration as well as blocking PD-L1 expression to regulate the tumor immune microenvironment." (PMID 37063421, 2023).
tumor (continued). "CRISPR mediated knockout of IGF2BP1 or ETV6::RUNX1 led to reduced tumor cell survival and reversal of prednisolone resistance." (PMID 37670323, 2023). "The oncofetal RNA-binding protein IGF2BP1 has been reported to be a driver of tumor progression in a multitude of cancer entities." (PMID 37515119, 2023). "The JNK/c-jun/METTL3/PD-L1/IGF2BP1 axis contributes to tumour immune escape in an m6A-dependent manner in BC." (PMID 37284313, 2023). "IGF2BP1 expression was significantly elevated in tumor samples and in both, tumor and non-tumor tissues, IGF2BP1 abundance appeared to be increased by HBV infection." (PMID 37515119, 2023). "Myeloid cell accumulation in the tumor microenvironment and skewing toward a macrophage phenotype was increased in Igf2bp1-KD tumors." (PMID 37503349, 2023). "Many studies have shown IGF2BP1 as a post-transcriptional fine-tuner that can enhance mRNA stability and translation to regulate the development and progression of tumor cells." (PMID 37137887, 2023). "IGF2BP1 enhances mesenchymal-like tumor cell phenotypes by promoting tumor cell migration, invasion, and metastasis." (PMID 35565249, 2022). "For example, tumor suppressor gene, circNDUFB2 interacts with the KH domains of IGF2BP1/2/3 in an m6A-dependent manner, and facilitates ubiquitination and degradation of IGF2BPs, thus leading to inhibition of tumor growth of lung cancer." (PMID 35541906, 2022). "Collectively, although substantial conservation of IGF2BP1 expression in tumor was found in previous studies, the effects of IGF2BP1 on tumor phenotypes were diverse among different tumor types." (PMID 36249006, 2022). "Although many of the cancer-related mRNA targets of IGF2BP1 were found to promote cell proliferation, migration and invasion, several were shown to take part in indirect suppression of tumor growth and metastasis." (PMID 36434608, 2022). "Among the clinical samples we collected, IGF2BP1 expression was also dramatically high in tumor tissue." (PMID 35368660, 2022). "Taken together, our findings indicate that IGF2BP1 plays an important role in regulating tumor-infiltration of immune cells in LUAD." (PMID 35154270, 2022). "As a post-transcriptional fine regulator, IGF2BP1 plays a role in remodeling tumor growth, chemotherapy resistance, and macroscopically, OS and recurrence of tumor patients." (PMID 36035182, 2022). "IGF2BP1 promotes tumor cell proliferation, invasion and chemoresistance through post-transcriptionally regulating its target RNA translation and stability." (PMID 36434608, 2022). "Here, we reported that the anti-tumor gene miR-193b-3p induces proliferation and differentiation of goat MuSCs, which phenocopies IGF2BP1 overexpression." (PMID 36555418, 2022). "It has been demonstrated before that IGF2BP1 enhances tumor cell proliferation through a m6A-dependent stabilization of MYC mRNA, one of its major known oncogenic targets." (PMID 35565249, 2022). "Among them, cluster 2 with higher IGF2BP1 show a lower level of immune cell infiltration, higher tumor purity, stronger drug resistance, and worse prognosis." (PMID 36249006, 2022). "In this research, IGF2BP1 was actively expressed in both LUAD clinical tumor tissues and cell lines." (PMID 35368660, 2022). "Combined targeting of IGF2BP1, EZH2, and Myc, a transcriptional activator of EZH2 and well-known target of IGF2BP1 cooperatively induces tumor cell apoptosis." (PMID 35565249, 2022). "We specifically noted that IGF2BP1 was more highly expressed in BRCA tissues in both unmatched (tumor, n = 1,109 vs. adjacent and normal, n = 292) and paired (112 paired tumors vs. adjacent normal) comparisons of TCGA-BRCA datasets compared to normal tissues." (PMID 36092925, 2022). "A high level of IGF2BP1 is often only observed during the process of embryo development and tumor formation; hence, IGF2BP1 used to be researched mainly as an oncofetal protein in several cancers." (PMID 36249006, 2022).
tumor (continued). "Of note, ectopic MYCN expression resulted in increased tumor volume and weight in xenograft model but IGF2BP1 silencing largely abrogated this effect." (PMID 35346372, 2022). "In pan-cancer studies, the high expression and tumor-promoting characteristics of IGF2BP1 in specific tumors make it a promising therapeutic target, but it is also inhibitory in some tumors." (PMID 36035182, 2022). "In the mouse subcutaneous transplanted tumor model, miR-454-3p controls IGF2BP1 through ERK and AKT signaling pathways and inhibits the proliferation, migration and apoptosis of ESCA cells." (PMID 36237306, 2022). "This work presents an avenue for improving the prognosis of Igf2bp1-expressing tumours in lung, and potentially other, cancer(s)." (PMID 34895045, 2022). "Our findings are in line with recent reports that IGF2BP1 is able to stimulate tumor cell proliferation in vitro and in vivo by enhancing E2F-driven gene expression, thereby promoting G1/S transition." (PMID 35565249, 2022). "Elevated protein levels of the ubiquitin E3 ligase adaptor FBXO45 promote tumor progression by stimulating ubiquitination of IGF2BP1 in hepatic cancer." (PMID 36293188, 2022). "Among them, IGF2BP1 has the most conserved “oncogenic” role in tumor cells, which induces a phenotype in mesenchymal tumor cells that includes altered actin dynamics, migration, invasion, proliferation, self-renewal, and anoikis resistance." (PMID 35433677, 2022). "In OS cells, IGF2BP1 was upregulated in tumor tissues and promoted the growth and metastasis of cancer cells." (PMID 35918761, 2022). "Recent studies have shown that increased IGF2BP1 expression is a poor prognosis predictor in several tumor types including lung adenocarcinoma, HCC and PDAC." (PMID 36434608, 2022). "Second, other studies are necessary to distinguish the effects of IGF2BP1 on the tumor immune infiltration pathway." (PMID 35154270, 2022). "To further discover the mechanisms through which LINC00261 exerts tumor suppressive functions, we performed an RNA pulldown assay followed by mass spectrometry and found that IGF2BP1 was a binding protein of LINC00261." (PMID 33122827, 2021). "Taken together, these data indicate that hypoxia-induced lncRNA KB-1980E6.3/IGF2BP1/c-Myc axis is essential for the maintenance of BCSCs, thus leading to tumor initiation and tumor growth in vivo." (PMID 33469161, 2021). "Consistently, knockout of IGF2BP1 in T24T cells led to a significant decrease in growth and tumor weight of subcutaneous xenograft tumors, and less lung metastatic counts and more survival of nude mice." (PMID 33853613, 2021). "To investigate IGF2BP1 functions in EC, we used lentivirus to upregulate IGFBPI expression in EC cell lines and constructed lentivirus expressing shRNA to silence IGF2BP1 expression in tumor cells." (PMID 33391523, 2021). "The results showed that the expression of IGF2BP1 was positively correlated with tumor size, the metastasis of lymph nodes, and advanced clinical stages of BC, respectively (Table." (PMID 33853613, 2021). "Immunohistochemical analyses in all three tumor cohorts confirmed the selective de novo expression of IGF2BP1 protein in ATC." (PMID 32719445, 2021). "Next, we compared the expression of IGF2BP1 in tumor tissues compared to that in matched normal tissues derived from 64 BC patients in our single-center." (PMID 33853613, 2021). "IGF2BP1 is not only related to the proliferation, migration, and invasion of tumor cells, but also closely related to the poor prognosis of patients." (PMID 34206803, 2021). "Consistently, in vivo assay demonstrated that overexpression of circPTPRA significantly impaired IGF2BP1-mediated promotion of subcutaneous xenograft tumor growth." (PMID 33853613, 2021). "By contrast, after silencing IGF2BP1, tumor weight significantly reduced and in turn Ki67 significantly reduced." (PMID 33391523, 2021).
tumor (continued). "Recent studies indicate that IGF2BP1 has the most conserved ‘oncogenic’ role of the IGF2BP family in tumor-derived cells, by affecting RNA stability, translatability, or localization." (PMID 33853613, 2021). "In tumor cells, the IGF2BP1-PTEN axis antagonizes the activation of Akt and HSP27, which modulates the actin cytoskeleton and influences cell migration." (PMID 33673232, 2021). "Further, the in vivo tumor xenograft mouse model also confirmed that the tumor inoculated with IGF2BP1 knockdown cells all exhibited smaller volume than the sides inoculated with control cells." (PMID 33747724, 2021). "The oncofetal IGF2 mRNA-binding protein 1 (IGF2BP1) is a crucial regulator of tumor and stem cell fate and its elevated expression in a multitude of tumors is associated with poor prognosis." (PMID 33829040, 2021). "The oncofetal IGF2 mRNA-binding protein 1 (IGF2BP1) promotes tumor progression in a variety of solid tumors and its expression is associated with adverse prognosis." (PMID 33829040, 2021). "Accordingly, the IGF2BP1/PTEN/Akt/HSP27 axis drives cell migration in different tumor types, including hepatocellular carcinoma, by regulating directionality of cell migration through lamellipodia formation and cell polarization." (PMID 33673232, 2021). "Next, we found that IGF2BP1 expression was significantly higher in tumor tissue samples than normal adjacent tissue samples in TCGA and positively correlated with tumor stage and OS." (PMID 33051595, 2021). "Next, we used tissue array and IHC to analyze the level of protein in IGF2BP1 in tumor tissues compared with endometrial samples." (PMID 33391523, 2021). "IGF2BP1 is an RNA-binding protein that participates in tumor progression, tumor cell proliferation and growth." (PMID 34416861, 2021). "The intensity of IGF2BP1 protein expression also positively correlated with tumor cell grade and FIGO stage." (PMID 33391523, 2021). "Immunohistochemistry analysis revealed that the IGF2BP1 protein was highly expressed in the tumor tissue samples compared with the adjacent normal tissue samples." (PMID 34779401, 2021). "The images showed that the IGF2BP1-silenced group developed fewer neoplasms than the control group, indicating that interfering IGF2BP1 blocked FBXO45-driven hepatocarcinogenesis." (PMID 34779401, 2021). "IGF2BP1 overexpression/knockdown can promote (and inhibit) cell proliferation and regulate the tumor cell cycle and cancer progression, both in vivo and in vitro." (PMID 33391523, 2021). "As IGF2BP1 showed increased expression in tumor parts, we next addressed the roles of IGF2BP1 in cancer progression and patient survival." (PMID 34203267, 2021). "We identified five differentially expressed genes in both sets of mutated tumours (PBinomial = 1.5 × 10−8), including CLIC5 and IGF2BP1." (PMID 34753926, 2021). "Consistent with its role supporting oncogene expression, IGF2BP1 was reported as a posttranscriptional driver of tumor cell proliferation, migration, metastatic potential, and therapy resistance." (PMID 32719445, 2021). "IGF2BP1 has been shown to implicate in proliferation, migration, invasion, adhesion, and apoptosis of tumor cells." (PMID 34141492, 2021). "The results of this study delineate novel mechanisms of circRNA/IGF2BP1-mediated regulation of tumor progression and provide opportunities for therapeutic intervention in BC." (PMID 33853613, 2021). "Different from its oncogenic role previously reported in colorectal and other cancers, IGF2BP1 had been reported to have tumor suppression roles." (PMID 34203267, 2021). "We showed that IGF2BP1 was overexpressed in tumor specimens compared to 13 paired normal parts by examining the immunoreactivity of IGF2BP1 (p = 0.045)." (PMID 34203267, 2021). "For example, the post-transcriptional control of IGF2BP1 expression by let-7 microRNAs is suggested to modulate tumor cell fate." (PMID 33853613, 2021).